TEKT4P2 (tektin 4 pseudogene 2)
Synonyms: formerly MAFIPL
Gene: Transcribed unprocessed pseudogene on chromosome 21 (9,068,414 to 9,073,609, reverse strand). Ensembl gene ENSG00000188681.
Diseases named in the same sentence as TEKT4P2 in open-access papers:
TEKT4P2 is named in the same sentence as 3 diseases in open-access papers, as found by Europe PMC text mining. Sharing a sentence is not in itself a finding about the gene and the disease. The quoted sentences say what the papers report.
cutaneous melanoma (1 paper, 2023). A primary melanoma arising from atypical melanocytes in the skin. "Therefore, similar to conventional cutaneous melanoma, methylation of the non–coding RNA TEKT4P2 could cause gene silencing and regulate other epigenetic markers, such as miRNAs in SM." (PMID 38203489, 2023). "It has been seen that TEKT4P2 levels decrease as the stages increase (I/II and III/IV compared with stage 0), and additionally, TEKT4P2 interacts with several miRNAs associated with the development of cutaneous melanoma, such as miR-193-3p, miR-194-3p or miR-194-5p." (PMID 38203489, 2023).
melanoma (1 paper, 2023). A malignant, usually aggressive tumor composed of atypical, neoplastic melanocytes. "TEKT4P2 is a pseudogen that has been described as a progression biomarker in cutaneous conventional melanoma." (PMID 38203489, 2023).
TEKT4P2 also shares sentences with these, for which no sentence is quoted: tumours (1 paper).